GRPR (gastrin releasing peptide receptor)
Diseases named in the same sentence as GRPR in open-access papers (continued):
Sharing a sentence is not in itself a finding about the gene and the disease.
breast carcinoma (78 papers, 2010 to 2026). "Radiolabeled gastrin-releasing peptide receptor (GRPR)-antagonists have been proposed for diagnostic imaging and radionuclide therapy—theranostics—of human tumors, including prostate (PC) and breast cancer (BC)." (PMID 34680243, 2021). "Recently, GRPR overexpression was found in 75.8% of breast carcinomas and was highly linked with ER positivity." (PMID 31652624, 2019). "The biodistribution of [67Ga]NeoBOMB1 was studied in severe combined immune deficiency (SCID) mice bearing GRPR-positive human breast cancer T-47D xenografts." (PMID 29137110, 2017). "Furthermore, GRPR activation has been linked to metastasis in prostate, colon, and breast cancers, though the specific mechanisms by which GRPR promotes metastasis are not yet fully understood." (PMID 39768218, 2024). "Taken together, these studies demonstrate that GRPR/FA dual-receptor targeted imaging perform better than its respective mono-specific variants and has potential for clinical translation for imaging and targeted radiotherapy of breast cancer." (PMID 33986665, 2021). "The bombesin ligand actively targeted gastrin-releasing peptide receptors (GRPr) on T-47D breast cancer cells, resulting in increased tumor uptake in PET/CT imaging and favorable tumor-to-background ratios, highlighting their utility in GRPr-targeted imaging." (PMID 40733120, 2025). "These developments gave hope for new tools in the clinical management of patients with GRPR-expressing tumors, such as prostate and breast cancer, which have high incidence of GRPR-overexpression." (PMID 39825204, 2025). "To validate the role of ERα in regulating GRPR in breast cancer, we did some experiments in MCF7 cells." (PMID 40500450, 2025). "In breast cancer, the co-expression of GRPR and folate receptors in various tumor subtypes has driven the development of radiopharmaceuticals targeting both receptors simultaneously." (PMID 40869454, 2025). "Bombesin (BBN) is a tetra-decapeptidethat demonstrates a strong preference for GRPR, and its absorptionin breast cancer has been confirmed in clinical studies involvinghumans." (PMID 39895089, 2025). "For breast cancer, it has been shown that a high level of GRPR expression in a primary tumor is a valuable tool for predicting metastasis probability and is strongly associated with estrogen receptor (ER) expression." (PMID 40775579, 2025). "The dual targeting of integrin αvβ3 and GRPR results in synergistic tumor targeting and detection, especially in cancers, such as prostate and breast cancers, that are characterized by co-expression of these receptors." (PMID 40869454, 2025). "An interest in radionuclide targeting of GRPR in breast cancer increased during recent years, owing to several factors." (PMID 40871022, 2025). "Targeting the gastrin-releasing peptide receptor (GRPR) is a promising approach for radionuclide therapy in prostate and breast cancers." (PMID 41231375, 2025). "In particular, GRPR are overexpressed in low-grade prostate cancer (PC) and estrogen-positive (ER+) breast cancer (BC)." (PMID 39976803, 2025). "First, GRPR is overexpressed, often at a high level, in a large fraction of malignant breast tumors, and its expression is typically preserved in metastases." (PMID 40871022, 2025). "Bombesin (BN, PYR-QRLGNQWAVGHLM-NH2) shows a strong affinity for mammalian GRPR, providing targeting capabilities for breast cancer (GRPR positive)." (PMID 39861688, 2024). "Clinical data demonstrates high uptake of GRPR-targeting antagonistic peptides in patients with estrogen receptor positive breast cancer both in primary lesions, lymph node and bone metastases." (PMID 38366299, 2024). "In vivo studies were conducted using breast cancer cell models, namely T47D (GRPR+/low αvβ3) and MDA-MB-435 (GRPR-/αvβ3+), with 18-F-FB-PEG3-RGD-BBN, 68Ga-NOTA-RGD-BBN, and 64Cu-NOTA-RGD-BBN." (PMID 38708130, 2024).
breast carcinoma (continued). "Their research proved that their nanomaterial was stable in human blood serum and able to selectively bind with GRPR-positive cells both in vitro in the T47D breast cancer cell line and in vivo in breast cancer tumor xenografts in BALB/c mice." (PMID 36834867, 2023). "This approach led to the successful targeting of GRPR-positive breast cancer and Ehrlich tumor cells." (PMID 36834867, 2023). "Gastrin-releasing peptide receptor (GRPR) is overexpressed in over 75% of breast cancers and can be efficiently targeted with 177Lu-Bombesin to deliver therapeutic radiation doses to malignant cells." (PMID 39355052, 2023). "Additional cancer-specific targets are explored for imaging, such as gastrin-releasing peptide receptor (GRPR) imaging in breast cancer patients with ER-positive tumors using the receptor antagonist [68Ga]Ga-RM26." (PMID 37195374, 2023). "The same substitution previously led to the SPECT radiotracer [99mTc]Tc-DB15 showing an attractive profile in GRPR-positive lesions in animal models and in breast cancer patients." (PMID 37509170, 2023). "Most importantly, the GRPR is expressed in high numbers in a variety of malignant tumors, including the frequently occurring prostate and breast cancer, small cell lung cancer, gastrinoma, gastrointestinal stromal tumors and others." (PMID 37242457, 2023). "They exploited [177Lu]Lu-DOTA-PAMAM-bombesin for the theranostic delivery of PTX to GRPR-positive T47D breast cancer cells." (PMID 36834867, 2023). "Breast cancers express gastrin-releasing peptide (GRP) hormone and gastrin-releasing peptide receptor (GRP-R), and its expression is associated with lymph node metastases." (PMID 36832085, 2023). "Such extensive design and preclinical screening of radiolabeled GRPR-antagonists has brought to light candidates eligible for clinical translation, mostly performed in prostate and breast cancer patients." (PMID 37242457, 2023). "Lahooti and colleagues used a class 2 antagonist with D-Phe12 substitution to successfully target their ultrasmall paramagnetic iron oxide nanoparticles (USPION) to GRPR-positive breast cancer xenograft in vivo." (PMID 36834867, 2023). "On the basis of these results, a clinical translation of 177Lu-AMTG is highly recommended to assess a potential improved therapeutic value for radioligand therapy of GRPR-expressing malignancies, such as prostate and breast cancer." (PMID 35027371, 2022). "Bombesin is a tetra-decapeptide with high binding affinity to GRPR, and its uptake in breast cancer has been demonstrated in human trials." (PMID 35890071, 2022). "Cellular uptake studies were performed using the T-47D human breast cancer cell line as it was described to express both the GRPR and NPY Y1 receptors, allowing the observation of the binding of the synthesized HBPLs." (PMID 35744852, 2022). "The gastrin-releasing peptide receptor has been found to be overexpressed in many types of tumor cells, including breast cancer cells." (PMID 35565232, 2022). "Among the different targets discussed for breast cancer imaging, the GRPR is the most promising novel target in our opinion." (PMID 33986665, 2021). "A study conducted on human breast cancer patient tissues reported that 51% of them (32/63) showed an overexpression of GRPR together with another receptor called the neuropeptide Y receptor subtype 1 (NPY(Y1)R)." (PMID 33986665, 2021). "GRPR is reported to be overexpressed in 96% of breast cancer tissues across all molecular subtypes of breast cancer." (PMID 33986665, 2021). "Preclinical studies have demonstrated these tracers’ potential to evaluate GRPR expression in GRPR-positive tumors, with some radiotracers being used in breast cancer imaging." (PMID 34771622, 2021). "111In-AMBA (111In t1/2 = 2.8 days) is a GRPR agonist that has been tested in an autoradiography study of 50 human breast cancer tissue specimens, with 96% (48/50) of them showing elevated GRPR levels." (PMID 33986665, 2021).
breast carcinoma (continued). "Diagnostic imaging and radionuclide therapy of prostate (PC) and breast cancer (BC) using radiolabeled gastrin-releasing peptide receptor (GRPR)-antagonists represents a promising approach." (PMID 34680243, 2021). "These independent studies indicate that GRPR is a highly promising target for theranostics of breast cancer." (PMID 33986665, 2021). "A nanosystem based on the 177Lu-labeled polyamidoamine (PAMAM) dendrimer (DN) loaded with paclitaxel (PTX) and functionalized on the surface with the DOTA-BBN peptide was designed for specific targeting to GRPR in T47D breast cancer xenografts." (PMID 33986665, 2021). "In autoradiography studies, GRPR was reported to be expressed at high density (>2000 dpm/mg tissue) in 74% (50 of 68) of breast cancer tissues from patients." (PMID 33986665, 2021). "Taken together, these strategies of using 177Lu-labeled chemotherapeutic drug-loaded nanosystems with BBN peptides for combined targeted therapy have shown promise in their application to GRPR-positive breast cancers." (PMID 33986665, 2021). "For example, 99mTc-BnR agonist indicated increased uptake in breast cancer cells and enhanced accumulations in studied tumours that overexpressed receptors of GRPR in animal models." (PMID 33925632, 2021). "In clinics, [68Ga]Ga-NOTA-PEG3-RM26 has recently been evaluated for GRPR imaging in patients with prostate and breast cancers." (PMID 33081166, 2020). "GRPR is normally expressed in different organs such as the pancreas and the stomach, and is overexpressed in various cancers, including prostate and breast cancers." (PMID 33081166, 2020). "Another concept for highly sensitive breast cancer imaging is the concomitant targeting of the GRPR and FRα, with both being overexpressed on this malignancy." (PMID 32751666, 2020). "Limitations for these biomarkers are, for example, that HER2 is overexpressed in 20–30%, and GRPR in around 76% of breast cancer tumors." (PMID 32990883, 2020). "Two promising theranostic couples represent relevant candidates for the therapeutic management of breast cancer patients: the gastrin release peptide receptor GRPR-targeting and PSMA-targeting agents." (PMID 32235331, 2020). "BBN is an attractive peptide for targeting the Gastrin-releasing peptide receptor (GRPR), which is overexpressed by a variety of tumors, including prostate and breast cancer." (PMID 32527027, 2020). "The expression of the GRPR has been reported in several cancers, including 72% to 96% of breast cancers." (PMID 32235331, 2020). "In a more recent study conducted in 34 women with suspected breast cancer, a novel GRPR antagonist, 68Ga-NOTA-RM26, was able to delineate primary breast tumors in 29/34 patients and lymph nodes metastases in 15/18 patients with node-positive disease." (PMID 30645633, 2019). "In total, our data point that GRPR targeting should be helpful for imaging breast cancer and more specifically so the ER-positive subtypes." (PMID 30645633, 2019). "The gastrin releasing peptide receptor (GRPR) is the cellular receptor of bombesin and therefore, its expression levels were analysed in different breast cancer cells to confirm its impact on migration." (PMID 31664083, 2019). "This in vitro study aimed to assess the binding of 18F-FDG and that of the GRPR antagonist 68Ga-RM2 on representative breast cancer samples." (PMID 30645633, 2019). "We have recently studied, using immunohistochemistry, the expression of GRPR ina large series of primary breast cancers and found that GRPR was overexpressed in 83.2% of ER-positive tumors but only in 12% of ER-negative tumors (p < 0.00001)." (PMID 30645633, 2019). "GRPR is an important receptor in breast cancer and is overexpressed in up to 96% of breast cancer patients." (PMID 31664083, 2019). "Our expression analysis in different breast cancer cell lines revealed that GRPR is significantly higher expressed in mesenchymal like breast cancer cell lines and correlates with the GRK5 expression." (PMID 31664083, 2019).
breast carcinoma (continued). "Tumors that can be targeted with GRPR-based radiotracers are notably, prostate cancer, breast cancer, lung cancer and colorectal cancer among others." (PMID 30645633, 2019). "We evaluated the HBPLs and their monospecific reference peptides in vitro regarding stability and uptake into different breast cancer cell lines and found that the 68Ga-HBPLs were efficiently taken up via the GRPR." (PMID 29973529, 2018). "Human breast cancer, for example, overexpresses in about 75% of all cases the gastrin-releasing peptide receptor (GRPR) and in 66–85% the neuropeptide Y receptor subtype 1 (NPY(Y1)R)." (PMID 29973529, 2018). "A very recent study investigating more than 1400 primary tumors from breast cancer patients emphasized the clinical relevance of GRPR as a target for breast cancer, especially in the case of estrogen receptor-positive tumors." (PMID 29137110, 2017). "This option is based on the high GRPR-expression documented in mammary carcinoma, especially in estrogen receptor-positive forms of the disease." (PMID 29137110, 2017). "Previous studies have demonstrated superior expression of the GRPR in T-47D cells among a series of eight human breast cancer cell lines." (PMID 29137110, 2017). "High gastrin releasing peptide receptor (GRPR) expression is associated with numerous cancers including prostate and breast cancer." (PMID 29097932, 2017). "Breast cancer cells, for example, over-express two receptors [gastrin-releasing peptide receptor (GRPR) in 70% breast cancer cells and integrin αvβ3 in 58% breast cancer cells]." (PMID 25849333, 2015). "This probe has been synthesized for targeted gastrin-releasing peptide receptor (GRPr) imaging and demonstrated specific GRPr targeting ability in vitro and in vivo in mice bearing T-47D breast cancer cells." (PMID 22180839, 2010). "Background/Objectives: Gastrin-releasing peptide receptor (GRPR) is overexpressed in breast cancer and might be used as a theranostics target." (PMID 40871022, 2025). "Notably, GRPR has emerged as a promising target for estrogen-receptor positive (ER+) breast cancer in a preclinical study using [55Co]Co- and [177Lu]Lu-DOTA-RM26." (PMID 40842662, 2025). "Other groups developed and characterized 99mTc-labeled BBN-folate conjugates (99mTc-BBN-folate) aiming at combining the targeting capabilities of BBN, directed toward GRPR, and folate, which targets folate receptors (such as FRα) commonly overexpressed in breast cancer cells." (PMID 40869454, 2025). "Therefore, we selected [99mTc]Tc-DB8 for clinical evaluation as a potential radiopharmaceutical for SPECT visualization of GRPR in breast cancer." (PMID 40871022, 2025). "Furthermore, in vitro targeting efficiency results revealed that Bom-targeted nanomicelles have a strong affinity toward GRPR-positive cells, suggesting their potential as active targeting contrast agents for precise imaging in breast cancer diagnostics." (PMID 38918821, 2024). "Furthermore, when this GRPR-targeted nanocarrier was injected into the BALB/c nude mice with MDA-MB-231 breast cancer xenografts, high-quality magnetic resonance and NIR fluorescence (NIRF) images of tumors were obtained with excellent contrast." (PMID 36834867, 2023). "In addition, this tracer can be used for molecular characterization of patients with hormone-driven breast cancer, where >80% of estrogen receptor positive lesions also express GRPR." (PMID 37175001, 2023). "Moreover, estrogen receptor–rich breast cancer (estrogen receptor being expressed in over 80% of all breast cancers), in particular, shows high GRPR expression, which is retained in 95% of nodal metastases." (PMID 35027371, 2022). "The gastrin-releasing peptide receptor (GRPR) is overexpressed in ER+/PR+ breast cancers." (PMID 35890071, 2022). "Overexpression of GRPR is also observed in 96% of all breast cancer tissues." (PMID 33986665, 2021).
breast carcinoma (continued). "Since GRPR are overexpressed across all subtypes of breast cancer, PRRT of GRPR might have a more general application for breast cancer treatment." (PMID 33986665, 2021). "Moreover, other receptors such as SSTR, GRPR, and Y1R have been described to be also overexpressed in breast cancer, and radiotracers targeting them are used ongoing in preclinical and in-first-human clinical studies." (PMID 31652624, 2019). "Furthermore, we found in MDA-MB-231 breast cancer cells that the inhibition of migration is mediated by the GPCR gastrin releasing peptide receptor (GRPR) leading to a reduced expression of migration regulating downstream targets like CDC42 and ROCK1." (PMID 31664083, 2019). "An elevated GRPR expression in breast cancer tissue worsens the prognosis." (PMID 31664083, 2019). "Recently, on the basis of these observations, the same authors investigated the potential of this molecule as an agent for imaging and therapy of GRPR-positive mammary carcinoma and reported the ability of [67Ga]NeoBOMB1 to specifically localize in the tumors of mice bearing T-47D breast xenografts." (PMID 31652624, 2019). "In this respect, the gastrin-releasing peptide receptor (GRPR) has attracted considerable attention as a promising biomolecular target in nuclear oncology, due to its high-density expression in frequently occurring human cancers (prostate and breast cancer)." (PMID 29137110, 2017). "Notably, tumor values did not decline from 1 to 24 h pi; Conclusions: [67Ga]NeoBOMB1 can successfully target GRPR-positive breast cancer in animals with excellent prospects for clinical translation." (PMID 29137110, 2017). "Accordingly, anti-GRPR radiopeptides for breast cancer theragnostics may soon become of high clinical impact." (PMID 29137110, 2017). "Finally, the correlation of GRPR (a known oncogene driving proliferation and angiogenesis) with this metabolic core suggests a compelling link between mitogenic signaling and mitochondrial bioenergetics in breast cancer." (PMID 41476662, 2025). "Besides being expressed by a very high percentage of primary tumors and corresponding metastasis, GRPR also showed considerably high receptor density in the analyzed breast cancer specimens (74% of tumors analyzed expressed GRPR with a mean density of 9,819 ± 530 dpm/mg tissue)." (PMID 38020178, 2023). "GRPR-PET/CT imaging may provide information about the ER status of breast cancer." (PMID 35565232, 2022). "99mTc-RGD-BBN may have the potential to make up for the deficiency of 99mTc-3P4-RGD2 in the detection of breast cancer with only GRPR positive expression (integrin αvβ3 negative)." (PMID 25849333, 2015). "In another study on breast cancer, 68Ga-BBN-RGD PET/CT allowed the demonstration of GRPR and integrin αvβ3 co-expression in a substantial portion of tumors." (PMID 40869454, 2025). "The gastrin-releasing peptide receptor (GRPR) is a promising target for this application because of its overexpression in several solid tumors, e.g., prostate and breast cancers." (PMID 37046825, 2023). "The gastrin-releasing peptide receptor (GRPR) is overexpressed in breast cancer, particularly ER+/PR+ breast cancers and their metastases." (PMID 35890071, 2022). "Currently, several markers, including HER2, GRPR, and somatostatin receptors (SSTR), are being investigated as possible targets for targeted radionuclide therapy in the treatment of breast cancer." (PMID 35565232, 2022). "As was referenced earlier, human breast cancer overexpresses 85% of NPY Y1 receptor but, as a matter of fact, it also overexpresses the gastrin-releasing peptide receptor (GRPR) in about 75% of cases." (PMID 35744852, 2022). "The radioconjugate 99mTc-BBN-FA (Peptides) has been synthesized to target the GRPR with the BBN portion and the FR with the FA portion for SPECT imaging in preclinical models of breast cancer." (PMID 33986665, 2021). "Therefore, an heterobivalent agent targeting GRPR and FR could improve breast cancer imaging." (PMID 33986665, 2021).